BCHE (butyrylcholinesterase)
Diseases named in the same sentence as BCHE in open-access papers (continued):
Sharing a sentence is not in itself a finding about the gene and the disease.
Sepsis (continued). "In critically ill COVID-19 patients, BChE activity is significantly decreased compared with healthy subjects, but also compared with other inflammatory conditions such as sepsis, burns, or trauma." (PMID 36140551, 2022). "A clear limitation for using BChE enzyme activity as a biomarker for potentially fatal sepsis is patients with dysfunctional livers." (PMID 29853783, 2018). "The missed time interval between the genuine inflammation and the clinical onset of sepsis presumably led to a failed initial BChE measurement and the resulting initial activity reduction." (PMID 29853783, 2018). "Using the POCT, BChE enzyme activity was measured at the starting time point and on days 1, 2, 7, 14, 21, and 28 following the clinical onset of sepsis." (PMID 29853783, 2018). "In addition, this study has yet to explain the mechanism of low BChE activity in children with septicemia, which requires further experimental research." (PMID 40861055, 2025). "The study found that low levels of butyrylcholinesterase on the first and third postoperative days were associated with an increased risk of developing SSIs, but not sepsis." (PMID 40342437, 2025). "In conclusion, in this prospective observational study, low BChE levels in the first and third day postsurgery were associated with an increased risk for the development of SSIs but not sepsis." (PMID 39229253, 2024). "Thus, the correlations of BChE activity with organ dysfunction, disease severity and survival are in line with previous results in sepsis, trauma, and burn patients." (PMID 36140551, 2022). "Our group has previously demonstrated that POCT-based BChE measurements could facilitate early detection of an emerging inflammatory response in patients with sepsis, major trauma, and burns." (PMID 36140551, 2022). "Studies suggested that BCHE may be an important therapeutic target for sepsis and has a significant predictive power for mortality in critically ill patients." (PMID 36062176, 2022). "The primary objective of the present investigation was to evaluate the potential therapeutic effects of cholinesterase inhibitors on PMN functions during the early phase of sepsis and to investigate the roles of AChE and BChE as inflammatory markers in CLP-induced sepsis." (PMID 30804708, 2019). "We estimated a critical BChE level of 1.661 kU/L (CI 0.5–0.8, 94% sensitivity, 48% specificity, AUC 0.7) to best predict patient outcome providing a benchmark criterion for early detection of potentially fatal sepsis measured at the admission." (PMID 29853783, 2018). "Probable reason could be that the exact time point of the clinical diagnosis of the sepsis (and the time point of the initial BChE measurement) differed from the actual time point of the primary inflammation." (PMID 29853783, 2018). "Systemic infection also contributes to BChE attenuation; BChE levels are significantly lower in those with bacteremia and could be useful for early detection of sepsis." (PMID 29736152, 2018). "Our ROC analysis, identifying the optimal BChE cutoff value of the measured BChE enzyme activity at the time point corresponding to the clinical onset of sepsis, suggests that a single bedside BChE measurement could early identify a high-risk patient." (PMID 29853783, 2018). "Surprisingly, the BChE assessment at the onset of sepsis proved more effective than these disease severity scores in discriminating between the surviving and the nonsurviving patient groups making it a valuable biomarker for the early detection of high-risk sepsis patients." (PMID 29853783, 2018). "We observed a comparable pattern in BChE and MR-proADM activity when compared between the survivor and the nonsurvivor patient groups, further validating the efficacy of the BChE in predicting survival of patients with sepsis." (PMID 29853783, 2018).
Sepsis (continued). "Previous studies have reported that low BChE levels on the first and third postoperative days are associated with an increased risk of prolonged ICU stay and postoperative complications, although findings regarding its relationship with sepsis remain inconsistent." (PMID 41010921, 2025). "Serum cholinesterase (butyrylcholinesterase, BChE, also known as ChE or pseudocholinesterase), an acetylcholine hydrolyzing enzyme, has been repeatedly described as a clinically relevant and prognostic biomarker in acute inflammatory entities such as sepsis, trauma, and burns." (PMID 36140551, 2022). "POCT approach, used to assess BChE activity, might further improve the therapy of the critically ill patients by minimizing time delays inherent with lengthy laboratory testing of other conventional markers of sepsis." (PMID 25762852, 2015). "DcR3 can be used as a biomarker for sepsis and can be used alone for early diagnosis or in combination with markers such as C-reactive protein (CRP), PCT, butyrylcholinesterase, presepsin, and pro-adrenomedullin." (PMID 37629097, 2023). "Among them, BCHE, AKT1, and IL2 are involved in the sepsis pathway, and LGALS3 is involved in both the sepsis and glycocalyx pathways." (PMID 36062176, 2022). "Characteristically for a negative acute phase protein, BChE activity has repeatedly been shown to be a prognostic biomarker for disease severity in acute inflammatory conditions such as sepsis, trauma, and burns." (PMID 36894596, 2023). "Considering the current evidence on the importance of esterase activities in patients with sepsis, most studies refer to changes in butyrylcholinesterase activity (BChE-activity), also called non-specific plasma esterase." (PMID 33203376, 2020).
type 2 diabetes mellitus (23 papers, 2005 to 2025). A type of diabetes mellitus that is characterized by insulin resistance or desensitization and increased blood glucose levels. "In line with our findings on glucose metabolism, higher BChE activity was reported to be linked to an increased risk for future type 2 diabetes." (PMID 40243328, 2025). "We found that decreased BChE activity early on in the critical illness course was independently associated worse acute brain dysfunction as shown by lower days alive and free of delirium or coma." (PMID 36474266, 2022). "BchE may be involved in the pathogenesis of type 2 diabetes either by way of amyloid fibrils or by modifying other risk factors of insulin resistance." (PMID 17096857, 2006). "For the link to glycaemia and type 2 diabetes, reports are inconsistent, with some reporting higher, while others report lower BChE activity." (PMID 40243328, 2025). "The high α-glucosidase inhibitory potential of S. hortensis methanol extracts and the strong BChE inhibition by essential oils particularly from S. Montana observed here implies their potential application in the management of type 2 diabetes and neurodegenerative disorders." (PMID 40953089, 2025). "In addition, it is reported that plasma and tissue concentrations of butyrylcholinesterase and AChE were elevated in type 2 diabetes and AD26." (PMID 32238886, 2020). "Thus, the inhibition of acetylcholinesterase, butyrylcholinesterase, tyrosinase, α-amylase, and α-glucosidase has been considered to mitigate the deleterious effects of type II diabetes and AD or as adjunctive treatment modalities." (PMID 29463056, 2018). "Similarly, the calyx and fruit extracts showed greater effectiveness in inhibiting the AChE, BChE, α-glucosidase, and α-amylase enzymes, indicating possible applications in the treatment of neurodegenerative diseases and metabolic disorders such as type 2 diabetes." (PMID 40227212, 2025). "In patients with the CHE2 C− phenotype and with type I diabetes mellitus, lower BChE activity was determined compared to the CHE2 C5− phenotype and to type II diabetes mellitus." (PMID 29780825, 2018).
cognitive decline (22 papers, 2017 to 2025). "We associated TOMM40 and SORCS1 with both amyloid and tau pathologies, whereas BCHE was associated with cognitive decline." (PMID 37629144, 2023). "TOMM40 and SORCS1 were associated with both amyloid and tau CSF biomarkers, while BCHE was associated with cognitive decline." (PMID 37629144, 2023). "Nonetheless, inhibitors of cholinesterases (AChE, BChE) have shown promise and compounds like donepezil, galantamine, rivastigmine and tacrine have been clinically approved for conditions associated with cognitive decline." (PMID 29056913, 2017). "Inhibition of BChE by unsaturated fatty acids might offer neuroprotection by extending acetylcholine’s action, potentially attenuating the cognitive decline associated with AD." (PMID 40116876, 2025). "This study showed that the BChE inhibition via gene KO and bambuterol administration enhanced the fear conditioning memory, the fear extinction memory and rescued the age-related spatial memory decline and the risk factors of age-related cognitive decline." (PMID 34062954, 2021). "Moreover, BChE was believed to compensate the function of AChE based on the experiment that AChE knockout mice could still survive with the normal level and localization of BChE, while silent BChE mutations in humans showed a slower rate of cognitive decline." (PMID 31311169, 2019). "MsA’s suppression of BChE, an enzyme overexpressed in late-stage AD and contributing to Aβ deposition and cognitive decline, represents a strategically important therapeutic intervention that has not been thoroughly documented for comparator compounds." (PMID 41007261, 2025). "Gnetol, scirpusin A, scirpusin B, and ε-viniferin all engage with cholinergic pathways, either by inhibiting BChE or modulating acetylcholine receptors, rendering them particularly pertinent for mitigating cognitive decline in AD." (PMID 40363789, 2025). "Given the high prevalence of cognitive decline in PD and other conditions like Lewy body dementia, selective BChE inhibition is a promising strategy for improving both cognitive and motor function." (PMID 40563465, 2025). "Acetylcholinesterase (AChE) and butyrylcholinesterase (BChE) are enzymes that degrade acetylcholine, leading to reduced neurotransmission and progressive cognitive decline." (PMID 39459522, 2024). "What is more, the effect of BCHE rs1803274 on cognitive decline, measured with MMSE in combination with donepezil treatment in MCI treatment was evaluated." (PMID 37629144, 2023). "Our results showed that BChE inhibition accelerates the fear extinction memory in mice and delays the cognitive decline in the early stages of aging." (PMID 34062954, 2021). "Inhibition of BChE is a promising target to increase the acetylcholinelevel and attenuate the cognitive decline, especially at a late diseasestage." (PMID 33829779, 2021). "Females with the BChE-wt/wt show a better benefit with rivastigmine than males, and BChE-K* male carriers show a faster cognitive decline than females." (PMID 32357528, 2020). "Treatment of AD focuses predominantly on reducing cognitive decline with acetylcholinesterase (AChE) and butyrylcholinesterase (BChE) inhibitors." (PMID 31683761, 2019). "For instance, while both AChE and BChE contribute to cholinergic dysfunction in AD, BChE is particularly important in the later stages of the disease, where its levels increase and correlate with the severity of cognitive decline." (PMID 40563465, 2025). "This study demonstrates that compounds derived from N. arbor-tristis can function as dual inhibitors of AChE and BChE, offering a safer and more sustainable alternative for managing AD and cognitive decline by exhibiting robust binding and favorable drug-like properties." (PMID 40700397, 2025). "Our study demonstrated that BChE KO mice and the BChE inhibitor (R)-bambuterol treated mice could ameliorate the age-related early cognitive decline and accelerate the fear of extinction." (PMID 34062954, 2021).
cognitive decline (continued). "Butyrylcholinesterase (BChE) also hydrolyses acetylcholine, so it may be desirable that drugs against cognitive decline also inhibit that enzyme." (PMID 28714881, 2017). "Additionally, increased BChE activity, especially in the hippocampus and temporal cortex, may exacerbate this cognitive decline by promoting amyloid-beta aggregation and plaque formation, which are key features of AD." (PMID 40002547, 2025). "Noteworthily, a clinical study described a very significant correlation between the rate of cognitive decline measured using the MMSE decrement per year and the activity of BChE in the temporal cortex of patients with Lewy body dementia." (PMID 38887858, 2024). "This study also suggested that (R)-bambuterol as a BChE inhibitor has the potential application in the treatment of post-traumatic stress disorder (PTSD) and early cognitive decline." (PMID 34062954, 2021).
metabolic syndrome (20 papers, 2005 to 2025). A cluster of metabolic risk factors for CARDIOVASCULAR DISEASES and TYPE 2 DIABETES MELLITUS. "Our study confirms that higher BChE activity is associated with liver fat accumulation and is present in patients with the metabolic syndrome." (PMID 40243328, 2025). "Numerous studies have demonstrated that genetic variations in BCHE influence its activity and are associated with BMI and metabolic syndrome." (PMID 38375199, 2024). "On the other hand, butyrylcholinesterase (BChE) is a serine hydrolase associates with lipid metabolism and indicators of metabolic syndrome such as body mass index, waist–hip ratio, waist circumference, weight, cholesterol, and triglyceride levels." (PMID 33066787, 2020). "Another key regulatory element in the lipid metabolism is a serine hydrolase known as Butyrylcholinesterase (BChE; EC 3.1.1.8), which is related to metabolic syndrome risk in obese patients)." (PMID 30445764, 2018). "BChE activity is repeatedly reported to be positively associated with TG, TC, BMI, and metabolic syndrome and is inversely associated with malnutrition, which can be also confirmed from our results." (PMID 28840123, 2017). "Previous studies have reported a significant association between serum BCHE activity and metabolic syndrome risk variables, such as high body mass index, plasma concentrations of triglycerides and HDL cholesterol, and blood pressure." (PMID 26497592, 2015). "The ratio of BChE to HDL cholesterol could be a marker of cardiovascular risk in the metabolic syndrome." (PMID 16150144, 2005). "Previous small studies suggested elevated levels of BChE in patients with fatty liver, obesity, and metabolic syndrome." (PMID 40243328, 2025). "In conclusion, our cross‐sectional and longitudinal results confirm that higher BChE activity is an estimate of liver fat accumulation and that it is present in patients with the metabolic syndrome." (PMID 40243328, 2025). "An increase in the availability or flux of free fatty acids to the liver, along with heightened lipogenesis from carbohydrates, can lead to dyslipidemia and elevated BChE activity." (PMID 40724174, 2025). "For instance, in metabolic syndrome (MetS) and type 2 diabetes (T2D), increased BChE levels correlate with markers such as leptin, glucose, cholesterol, inflammatory mediators like interleukin-6 (IL-6), and oxidative stress indicators such as superoxide anion." (PMID 40612057, 2025). "Bearing that in mind, we have decided to estimate cholinesterase activities in blood of children with metabolic syndrome and compared these effects with changes in AChE and BChE activities in children supplemented with A. melanocarpa extract." (PMID 29780825, 2018). "In small studies, high BChE has long been suspected in hepatic steatosis and metabolic syndrome." (PMID 40243328, 2025). "Therefore, we examined the relationships of BChE activity with glucose metabolism and metabolic syndrome in cross‐sectional and two longitudinal studies." (PMID 40243328, 2025). "Inversely, patients with metabolic syndrome have been shown to express increased BChE activities, such that reductions in their BChE might be masked." (PMID 25762852, 2015). "The BChE activity was not measured prior to inflammation; therefore, we cannot exclude the possibility that patients with metabolic syndrome might show false elevated BChE activity levels during the systemic inflammatory disease." (PMID 25762852, 2015). "Lastly, serum biomarkers linked to metabolic syndrome, hepatic steatosis, and mood disorders, such as butyrylcholinesterase (BChE), were not available in the KNHANES dataset and therefore could not be analyzed." (PMID 41011102, 2025). "Butyrylcholinesterase is an enzyme that may serve as a marker of metabolic syndrome." (PMID 16150144, 2005).
metabolic syndrome (continued). "There are no reports of changes in the activity of butyrylcholinesterase (BChE) in children and adolescents with metabolic syndrome especially after supplementation with extract from Aronia melanocarpa." (PMID 29780825, 2018). "However other studies have suggested BchE may not have a direct pathophysiological role in the development of metabolic syndrome, but may be considered as secondary markers for this syndrome in obese individuals." (PMID 21569551, 2011). "However recent studies have suggested BchE may not have a direct pathophysiological role in the development of metabolic syndrome, but may be considered as secondary markers for this syndrome in obese individuals with the CHE2 C5- phenotype." (PMID 16150144, 2005).
Hypertension (17 papers, 2014 to 2025). The presence of chronic increased pressure in the systemic arterial system. "However, after adjustment for hypertension and albumin the association of butyrylcholinesterase with mortality was even more distinct." (PMID 24479557, 2014). "Increased BChE activity has also been observed in animal models of hypertension induced by Nω-Nitro-L-arginine methyl ester hydrochloride (L-NAME)." (PMID 40698664, 2025). "Levels of butyrylcholinesterase showed a significant correlation with albumin, hypertension, hypercholesterolemia, and weak but significant inverse associations with EuroSCORE, ECMO duration, aspartate aminotransferase (ASAT), and γ-glutamyltransferase." (PMID 24479557, 2014). "In accordance with these data, we confirmed a significant correlation between serum butyrylcholinesterase levels and history of hypertension." (PMID 24479557, 2014). "Apart from univariate association with age (p = 0.037) arterial hypertension (p = 0.045) and female sex (p = 0.040), analysis of BChE decline did not provide any substantial new findings compared with postoperative activities." (PMID 38424490, 2024). "In regard to cardiovascular risk factors, younger patients with arterial hypertension show higher values of BChE activity, than both young patients without hypertension and patients within the remaining age strata." (PMID 25933219, 2015). "Our study indicates that BChE may be a shared target for both AD and hypertension." (PMID 32143538, 2020).